IDO1 (indoleamine 2,3-dioxygenase 1)
Diseases named in the same sentence as IDO1 in open-access papers (continued):
Sharing a sentence is not in itself a finding about the gene and the disease.
infection (continued). "In addition, in pregnancy, IDO1 expression in endothelial cells may inhibit extravasation of microbial pathogens from the blood into the tissue through the depletion of tryptophan in the local tissue adjacent to the blood stream, and this may contribute to protection of the fetus against infection." (PMID 32260288, 2020). "Current evidence suggests that probiotics/prebiotics can improve microbial translocation, regulate intestinal microbes, promote CD4+ T cell reconstitution, and reduce the activity of indoleamine 2,3-dioxygenase-1 (IDO-1), contributing to the protection of Th17 cells during infection." (PMID 33193273, 2020). "Similarly, IDO1 showed sixfolds increase, whereas LIF, IL6, CCL2, and VEGF each showed more than threefold increase in expression post infection." (PMID 32546788, 2020). "Expression levels of (A) IDO1 and (B) TGF-β1 were measured from vaginal swab samples of women who were Chlamydia positive at first visit (time point 0), cleared their infection after azithromycin treatment, and were invited for follow up visits (1–4 months post infection clearance)." (PMID 30832593, 2019). "Parasites that entered inside tyrosine mutant-IDO1 expressing cells, were not able to form PVs in process of infection." (PMID 30770800, 2019). "In this study, we measured the expression levels of IDO1 and immune regulatory markers, transforming growth factor β1 (TGF-β1) and forkhead box P3 (FoxP3), in vaginal swab samples of C. trachomatis-infected women, with either single or repeated infection." (PMID 30832593, 2019). "Although not significant, C. trachomatis positive patients with single infection (CT-P) had a trend of higher IDO1 expression levels in comparison to C. trachomatis negative patients." (PMID 30832593, 2019). "Our observation that IFNγ-dependent responses, such as the induction of IDO1, are not affected in bystander cells suggests a critical role for these cells in limiting the spread of infection." (PMID 29855501, 2018). "IDO1 induction in response to IFNγ is not affected in bystander cells permitting tryptophan depletion in the infection microenvironment." (PMID 29855501, 2018). "Paralleling trends in the CNS of these animals, we found that upstream enzymes (IDO1, KMO, and KYNU) displayed significant mRNA upregulation during at least one phase of infection, while downstream enzymes (HAAO and QPRT) were either downregulated or unchanged." (PMID 28066416, 2016). "At day 5 post-infection, no change in red blood cells was found, while blood platelets and lymphocytes were equally decreased in WT and IDO1-KO mice." (PMID 26914138, 2016). "We postulated that the increase of IDO1 activity in vivo was a secondary event following the release of IFN-γ rather than a direct induction by the infection itself." (PMID 22860140, 2012). "In M. tuberculosis-infected mice, non-haematopoietic cells express IDO-1 during the chronic phase of infection." (PMID 22649518, 2012). "Considering that monocytes appear to be the main source of active IDO1 in human peripheral blood, THP-1 cells were used as an experimental model of infection in further testing of our hypothesis." (PMID 22860140, 2012). "Compared with the control group, the expression of IDO1 in the infection group was significantly increased, the expression of IDO1 in the Lactobacillus group was significantly decreased compared with the infection group (P<0.01), and there was no significant change in the tryptophan group." (PMID 39114658, 2024). "Limited expression of HIF-1α and IDO1 were observed regardless of infection status." (PMID 36989320, 2023). "The activity of IDO1 is irrelevant under basal conditions, but strongly inducible by several inflammatory stimuli, such as interferon-γ (IFN-γ), lipopolysaccharide (LPS), tumor necrosis factor α (TNF- α), proinflammatory interleukins (ILs), infection, and transforming growth factor β (TGF-β)." (PMID 34576041, 2021).
infection (continued). "Mining a single cell RNA-seq (scRNA-seq) dataset (GSE123688) confirmed a significant infection-induced upregulation of Tdo2 in hepatocytes and further confirmed that Ido1 is not expressed whereas Ido2 seems to be very lowly expressed in hepatocytes and not differentially regulated." (PMID 33045014, 2020). "The increased expression levels of IDO1, TGF-β1 and FoxP3, in women who cleared their infection, may suggest that during the combined effect of highly expressed levels of IDO1 and TGF-β1, this induces the expression levels of FoxP3, an indicator of regulatory immune response." (PMID 30832593, 2019). "For example, Ido1 has anti-microbial activity in a variety of infectious diseases, and LCN2 has been reported to be as a bacteriostatic protein for protection of airways against infection by E. coli; 3) Components response to cytokines and reactive oxygen species were significantly modulated." (PMID 23826353, 2013). "Since monocytes are the main source of active IDO1 in human peripheral blood and also seem to be a potential target of infection to carry the intracellular organisms to remote organs, a human macrophage cell line THP-1 was used as a model in subsequent in vitro infection experiments." (PMID 22860140, 2012). "There are two other tryptophan-metabolising enzymes, IDO-2 and TDO (tryptophan dioxygenase), that could drive the kynurenine pathway in the absence of IDO-1, but their role in immunity to infection is not well understood." (PMID 22649518, 2012). "Moreover, given that assessment in T. gondii numbers in PVs and the infection rate have been established as being indicative of the restriction of parasite replication and of parasite elimination/killing, IDO1 is required for T. gondii replication control rather than parasite elimination." (PMID 30283439, 2018). "Immune checkpoint molecules including PD1, PDL1, CTLA4, LAG3, and IDO1 were significantly upregulated in the JBNU-22-N01-infected group compared with the negative control and VR2332 infection at 7 dpi." (PMID 40459260, 2025). "At 14 dpi, all infection groups showed almost identical upregulated mRNA expression profiles of PD1, PDL1, CTLA4, LAG3, and IDO1 compared with the negative control." (PMID 40459260, 2025). "There is a possibility that IDO1 inhibits the synthesis of the marker LacZ protein by tryptophan depletion, but not HIV-1-based vector infection." (PMID 35883685, 2022). "We therefore measured IFN-γ expression levels in response to infection in our in vitro model and found that in PBMCs alone, C. trachomatis infection did not affect IFN-γ expression levels, whereas IDO1 levels were significantly upregulated." (PMID 30832593, 2019). "In contrast, at early or late stages of MuLV-infection IDO enzyme activity and IDO1 gene transcription in CNS tissues were not elevated significantly over basal levels." (PMID 27168185, 2016). "We found that in women with repeated infections and in women who have cleared their infection after antibiotic treatment, immune-regulatory markers, IDO1, TGF-β1 and FoxP3 were significantly upregulated in comparison to C. trachomatis negative women and in those with single current infection." (PMID 30832593, 2019). "Importantly, PCPA administration failed to exacerbate infection and immunopathology in condition of AhR blockade, whereas 5-HTP administration failed to improve resistance to infection and pathology in condition of IDO1 blockade." (PMID 37717018, 2023).
infectious disease (23 papers, 2012 to 2025). A disorder directly resulting from the presence and activity of a microbial, viral, or parasitic agent in humans. "The dual role of IDO1 in infectious diseases might be associated with the type of pathogen and the stage of disease development, indicating the complexity of its mechanisms of action." (PMID 40715093, 2025). "In autoimmune and infectious diseases, it has been demonstrated that PRRs, such as Dectin-1 and TLRs, can influence IDO-1-dependent or IDO-1-independent mechanisms of MDSC15,23,24,49." (PMID 37524886, 2023). "Recent research findings have shown that overexpression of IDO1 in DCs facilitates T cell anergy in non-infectious disease models." (PMID 36439161, 2022). "Such IDO-1-mediated modulation of innate immune responses was initially demonstrated in infectious diseases, but further evidence identified IDO as a mediator of immune tolerance." (PMID 33920505, 2021). "Originally known for its regulatory function during pregnancy and chronic inflammation in tumorigenesis, the activity of IDO1 seems to modify the inflammatory state of infectious diseases." (PMID 23476103, 2013). "In this paper, current knowledge about the role of IDO1 and its metabolites during various infectious diseases is presented." (PMID 23476103, 2013). "Based on these findings, it was speculated that the constitutive expression of IDO1 in the female genital tract could modify immune cell activation and may protect against infectious diseases." (PMID 39061522, 2024). "Considering that the activity of IDO1 is able to modify the inflammatory state during infectious diseases, understanding in detail the mechanisms of its circadian regulation will be of great interest for the design of therapeutic strategies in different immune-related pathologies." (PMID 36896128, 2023). "However, there is currently limited research on the role of IDO1 in EBV infectious diseases." (PMID 40715093, 2025). "The identification of effective and non-toxic IDO1 inhibitors designed to treat infectious diseases is an urgent need." (PMID 35281455, 2022).
neurodegenerative disease (15 papers, 2015 to 2026). A disorder of the central nervous system characterized by gradual and progressive loss of neural tissue and neurologic function. "IDO1 thus becomes involved in two hallmarks of neurodegenerative diseases, inflammation and reduced brain glucose metabolism." (PMID 41543363, 2026). "Chronic activation of IDO-1 leads to subsequent activation of other enzymes producing neuroactive metabolites that can affect the severity of neurodegenerative diseases." (PMID 36153399, 2022). "Since the discovery of IDO1 in 1967, the development of IDO1 inhibitors has been mainly focused on the treatment of neurological disorders and neurodegenerative diseases." (PMID 32047753, 2019). "In conclusion, inhibiting the kynurenine metabolic pathway is considered a potential therapeutic strategy, with inhibition of IDO1 activity being an important target for neuroprotective treatments to alleviate symptoms of neurodegenerative diseases and neuroinflammation." (PMID 39940736, 2025). "Two enzymes, IDO1 and 2, attracted our attention because, as is evident from the published data, they are important in the development of neurodegenerative diseases, however, their role in neuropathic pain has not been established." (PMID 30050435, 2018).
neurological disorders (15 papers, 2011 to 2025). "Inhibition of IDO-1 activity is thus an attractive therapeutic strategy in treating HIV-associated neurological disorders." (PMID 22649518, 2012). "Recent studies have proposed that IDO1 is involved in neurological diseases." (PMID 33679331, 2021).
bacterial infection (14 papers, 2012 to 2025). "Enhanced IDO-1 activity during bacterial infection might limit tryptophan availability to T cells and thereby regulate T cell proliferation." (PMID 22649518, 2012). "LPS-triggered tolerance, which protects mice against immunopathology in bacterial infections, requires the combined effects of AHR and IDO1 to downregulate early inflammatory gene expression." (PMID 37207185, 2023).
cardiovascular diseases (13 papers, 2017 to 2025). "Compared to the general population, IDO1 activity is elevated in individuals with obesity, with a more pronounced effect observed in premenopausal women, further amplifying the interaction between them and exacerbating the risk of cardiovascular diseases." (PMID 38883986, 2024). "Although research on IDO1 inhibitors has progressed to phase III clinical trials, the controversy surrounding their mechanisms in cardiovascular disease has prevented clinical trials using IDO1 inhibitors for treating cardiovascular diseases." (PMID 38883986, 2024). "Lines of evidence suggest that IDO1 and the Kyn pathway significantly contribute to cardiovascular diseases and thrombus formation." (PMID 34630411, 2021). "For example, in vivo experiments using animals have demonstrated that targeting IDO1, KMO, KYNU, and KAT II KP enzymes can regress cardiovascular diseases by reducing inflammation." (PMID 34630411, 2021). "The potential of IDO1 to be a link between NASH and cardiovascular disease has never been investigated." (PMID 35563591, 2022).
adenocarcinoma (12 papers, 2014 to 2025). A common cancer characterized by the presence of malignant glandular cells. "The only statistically significant association we found was between a low Kyn/Trp ratio and a low IDO1 expression in the adenocarcinoma group (p = 0.013)." (PMID 33922388, 2021). "Genomic loss of JAK1 occurs in some adenocarcinoma and CRPC cell lines, explaining why some cell lines, particularly adenocarcinoma cell lines, with a deficient IFN-γ response fail to produce PD-L1/IDO-1." (PMID 33692219, 2021). "In agreement with studies carried out in adenocarcinoma cell lines, we found similar upregulation of genes such as IDO1, GBP1, CXCL9, CXCL10, and CXCL11 in response to IFN-γ, all of which are also known to be upregulated in IBD patients." (PMID 33396621, 2020). "Additionally, we used BAY-17085, an inhibitor of p65 nuclear translocation, to further validate the role of p65 in inducing IDO1 in adenocarcinoma cells." (PMID 37985999, 2023). "We observed a significant upregulation of IDO1 mRNA in A549, H1792, H1838, H2347, HCC364 and HCC827 adenocarcinoma cell lines incubated with IL-1β." (PMID 37985999, 2023). "Since both IDO1 and TDO2 can catalyze the conversion of Trp to Kyn, we asked whether IL-1β can also induce TDO2 expression in adenocarcinoma cells." (PMID 37985999, 2023). "Additionally, in comparison with normal samples, the expression level of CCR7, CXCL10, IDO1, and MMP9 were increased in phases of adenocarcinoma’s tissue, while the expression level of CXCL9 and VCAM1 were decreased." (PMID 31214045, 2019).
metabolic disease (10 papers, 2019 to 2025). A congenital disorder (due to inherited enzyme abnormality) or acquired (due to failure of a metabolically important organ) disorder resulting from an abnormal metabolic process. "Similarly, most previous studies have focused on the tissues that specifically express IDO1, such as the liver, muscle, and adipocytes, while the contribution of the gut microbiota in the diet-associated Trp metabolic disorder has been less investigated." (PMID 37468922, 2023). "Recent research from Soraya Taleb's laboratory revealed IDO1's unexpected function in metabolic disorders, which brought our eyes back to the metabolic function of IDO1 in metabolic disease." (PMID 38706741, 2024). "Both fresh GE and AGE could reverse the metabolic disorder in the tryptophan pathway induced by CRS, but only AGE significantly reduces IDO1 expression induced by CRS stimulation." (PMID 37033659, 2023). "Mice with an intact bone-marrow derived immune system, but lacking IDO1 in all other tissues, displayed a similar protection from HFD-induced metabolic disease as the mice with global IDO1 deletion." (PMID 31921154, 2019).
psychiatric disorder (10 papers, 2020 to 2026). A disorder characterized by behavioral and/or psychological abnormalities, often accompanied by physical symptoms. "This activation also increases activity of the kynurenine pathway (KP) and alters expression of key KP enzymes such as indoleamine 2,3-dioxygenase (IDO-1) and kynurenine 3-monooxygenase (KMO), both major contributors in the pathology of several neurodegenerative and psychiatric disorders." (PMID 41602856, 2026).
immune dysfunction (9 papers, 2013 to 2024). "Therefore, an understanding of the regulation of IDO1 and the subsequent biochemical reactions is essential for the design of therapeutic strategies in certain immune diseases." (PMID 23476103, 2013). "The activity of the indoleamine-2,3-dioxygenase-1 (IDO-1), an enzyme catabolising the essential amino-acid tryptophan into immunosuppressive kynurenines, has been recognized as a key factor of HIV immune dysfunction and damage to the gut mucosa." (PMID 32156291, 2020). "We believe that further findings on the mechanism of immune regulation by IDO1 and TRP metabolites might contribute to the implementation of a novel therapy protocol, which would target several immune disorders." (PMID 23476103, 2013).
kidney (8 papers, 2014 to 2025). "To investigate the effect of IDO1 on AE progression, we extracted RNA from the liver cysts of infected mice and measured the levels of 14-3-3 and II/3-10." (PMID 40597301, 2025). "The Trifecta Study emphasises the importance of molecular markers such as IDO1 in understanding and monitoring kidney transplant rejection." (PMID 39064305, 2024). "Gal-3 is essential for the TLR-2-dependent activation of renal dendritic cells, stimulating the indoleamine 2, 3-dioxygenase 1 (IDO1)/kynurenine (KYN) pathway, which subsequently enhances the proliferation of immunosuppressive Tregs during kidney injury." (PMID 40911105, 2025).
inflammation (7 papers, 2016 to 2024). Aberrant reaction of the microcirculation characterized by movement of fluid and leukocytes from the blood into extravascular tissues. "We reported previously that ZnONPs-induced pulmonary inflammation is mediated through inflammatory cytokine–indoleamine 2,3-dioxygenase (IDO1)–aryl hydrocarbon receptor (AhR) loop in the lung macrophages and epithelial cells." (PMID 32414036, 2020).
hematological malignancies (5 papers, 2014 to 2022). "Targeting hematological malignancies with IDO1 or COX2 polyphenolic inhibitors may be another therapeutic option." (PMID 36386899, 2022). "IDO1 is overexpressed in more than 50% of tumors including hematological malignancies." (PMID 36386899, 2022). "It is presently unknown whether LSCs in AML and CML rely on IDO1 expression as an immune evasion strategy and whether patients with hematological malignancies may benefit from therapy with IDO1-targeting small-molecule inhibitors." (PMID 29466292, 2018). "In hematological malignancies, common immune checkpoint targets are reported mainly include PDCD1, IDO1, PD-L1, LAG3, and CTLA-4." (PMID 36061194, 2022). "The expression levels of IDO1 and KYN and the activity of KP have also been investigated in the context of hematological malignancies, in particular in AML, where an extensive review of the literature has been recently performed." (PMID 34445444, 2021). "Subsequent studies showed that serum KYN levels alone or in combination with expression levels of IDO1 can have an important prognostic role in AML and also in other hematological malignancies such as adult T-cell leukemia/lymphoma, peripheral T-cell lymphoma and in diffuse large B-cell lymphoma." (PMID 34445444, 2021).
liver (5 papers, 2016 to 2025). "Our results indicated that Gal-3 is required for TLR-4-dependent activation of IDO-1/KYN pathway in colon-infiltrating DCs and for consequent Tregs-based suppression of Th1/Th17 cell-driven colon inflammation." (PMID 31336879, 2019).
renal diseases (5 papers, 2015 to 2023). "In fact, IDO1 has been found to play different roles in different renal diseases." (PMID 31555267, 2019). "There is some evidence that IDO1 and/or IDO2 activity can affect complement activation in different diseases, however the exact mechanism remains unknown and no study has specifically investigated the role of IDO on complement in renal disease." (PMID 31555267, 2019).
CNS tumors (4 papers, 2012 to 2023). "IFNγ-mediated induction of IDO1 was strongly reduced by mTOR inhibition with rapamycin suggesting that functional relationship between mTOR and IDO1 might be specific of MB among CNS tumors." (PMID 27174915, 2016).